DANCR (differentiation antagonizing non-protein coding RNA)
Diseases named in the same sentence as DANCR in open-access papers (continued):
Sharing a sentence is not in itself a finding about the gene and the disease.
breast carcinoma (continued). "Secondly, in TNBC cells, knocking down DANCR significantly reduced EMT, cancer stemness, and inflammation, suggesting its essential role in maintaining these malignant phenotypes of advanced breast cancer cells." (PMID 31860165, 2020). "DANCR induced down‐regulation of SOCS3‐induced inflammatory response and multiple malignant phenotypes in breast cancer cell." (PMID 31860165, 2020). "This revealed that two of the seven CSC-lncRNAs, NRAD1/LINC00284 and DANCR, are significantly enriched in TNBC/basal-like breast cancers." (PMID 32244924, 2020). "In the present study paper, we found that DANCR was obviously overexpressed in TNBC tissues and breast cancer cells compares with relative normal tissues and breast cells, and higher DANCR level suggested poorer prognosis." (PMID 30910842, 2019). "To better research the functions and mechanism of DANCR on breast cancer cells, we selected two cell lines used for next study: one TNBC cell line–MDA-MB-231 and one ER-positive breast cancer cell line–MCF-7." (PMID 30910842, 2019). "To further demonstrate the involvement of DANCR in TNBC, we tested DANCR expression in six breast cancer cell lines (BT549, MCF7, T47D, MDA-MB-231, MDA-MB-453, and MDA-MB-468) and a normal mammary epithelial cell line (MCF10A)." (PMID 30518934, 2018). "Here, we found that lncRNA DANCR was significantly overregulated in TNBC tissues and cell lines compared with normal breast tissues or other type of breast cancer." (PMID 30518934, 2018). "Therefore, DANCR competitively binds to miR-216a-5p to upregulate OCT4 expression, thereby affecting the biological behaviours of breast cancer." (PMID 35907897, 2022). "Furthermore, using ChIP and RNA immunoprecipitation, we examined the reciprocal regulation between DANCR and suppressor of cytokine signaling 3 (SOCS3) in breast cancer." (PMID 31860165, 2020). "DANCR is regulated by c-Myc in lymphoma, but to our knowledge, this has not been shown in breast cancer." (PMID 32244924, 2020). "First, DANCR expression level was examined in breast cancer tissues and paired adjacent non-tumor tissues both obtained from 57 TNBC patients." (PMID 30910842, 2019). "Our results showed that DANCR was up-regulated in TNBC tissues and breast cancer cells compared with normal breast tissues and cells, and higher DANCR level suggested poorer prognosis, implying that it was promising to be a novel biomarker used for TNBC diagnosis and prognosis." (PMID 30910842, 2019). "In our work, we selected two breast cancer cell lines: one TNBC cell line–MDA-MB-231 and one ER-positive breast cancer cell line–MCF-7, in order to study DANCR functions on breast cancer and explore whether it was specific for TNBC." (PMID 30910842, 2019). "Moreover, knockdown of endogenous DANCR inhibited proliferation and invasion of MDA-MB-231 in vitro and enhanced tumorigenesis of xenograft breast cancer in mouse model." (PMID 28760736, 2017). "We first found that DANCR were overexpressed in all of the four breast cancer cell lines compared with in Hs578Bst cells, of them MCF-7 and T47D had about 10-folds of DANCR expression level, however MDA-MB-231 and MDA-MB-468 had over 50-folds of DANCR expression." (PMID 28760736, 2017). "Hence, lncRNAs, such as DANCR, HOTAIR, H19, and GAS5, are identified as key regulators of autophagy in breast cancer, and further research needs to be carried out to identify their potential in breast cancer diagnosis and treatment." (PMID 36899946, 2023). "The results showed that five lncRNAs including HOTAIR, DANCR, PVT1, LINC00511, and NEAT1 and 16 miRNAs and five of their targets—VEGFA, BTG2, E2F3, IRAK1, and SMAD4—have significantly different expression patterns in normal individuals compared to those with breast cancer." (PMID 36726376, 2023). "Therefore, inhibiting DANCR or up‐regulating SOCS3 may simultaneously target all three metastasis‐related phenotypes and improve the prognosis of breast cancer patients." (PMID 31860165, 2020).
breast carcinoma (continued). "Therefore, understanding the mechanisms controlling DANCR expression during breast cancer development, effectively targeting these mechanisms, and developing strategies to either suppress DANCR or up‐regulate SOCS3 may prevent tumorigenesis and suppress the malignant progression of breast cancer." (PMID 31860165, 2020).
hepatocellular carcinoma (24 papers, 2017 to 2024). A malignant tumor that arises from hepatocytes. "The high expression of DANCR has been linked with tumor progression and poor prognosis in colorectal cancer, hepatocellular carcinoma, and gastric cancer." (PMID 33638615, 2021). "DANCR was reported to associate to the CTNNB1 gene in hepatocellular carcinoma, thereby protecting it from inhibitory miRNAs; however, we were unable to detect an association under our conditions (data not shown)." (PMID 33302540, 2020). "Furtherance, DANCR also functioned as ceRNA to promote proliferation of hepatocellular carcinoma through suppressing cell apoptosis and cell cycling." (PMID 37215458, 2023). "For example, lncRNA-DANCR is overexpressed in tumor initiation cells, identifying DANCR as a prognostic biomarker and therapeutic target for hepatocellular carcinoma treatment." (PMID 36105077, 2022). "Another study in hepatocellular carcinoma cells has shown over-expression of DANCR and ATG7, and down-regulation of miR-222-3p." (PMID 35590326, 2022). "Another study in hepatocellular carcinoma has shown up-regulation of DANCR in tumor and plasma samples in correlation with microvascular and hepatic capsule invasion." (PMID 35590326, 2022). "Expression assays in hepatocellular cancer tissues have revealed over-expression of DANCR and ATG7, and down-regulation of miR-222-3p." (PMID 35590326, 2022). "For example, DANCR was verified to interact with 3′UTR of CTNNB1 mRNA in hepatocellular carcinoma, thus competitively blocking miRNA site and reversing miRNA-mediated CTNNB1 suppression." (PMID 34722539, 2021). "DANCR expression was highly correlated with microvascular and liver capsule invasion of hepatocellular carcinoma." (PMID 33123287, 2020). "Functionally, knockdown of DANCR inhibited hepatocellular carcinoma cell proliferation and invasion by suppressing β-catenin signaling." (PMID 33123287, 2020). "Similar to CRC, oncogenic DANCR within hepatocellular carcinoma (HC) has also been found to have multiple regulating targets." (PMID 31799189, 2019). "The recent studies suggest that DANCR expression is upregulated in hepatocellular carcinoma, prostate cancer, and colorectal cancer." (PMID 29416741, 2018). "DANCR is suggested as a critical regulator of the stemness features of hepatocellular carcinoma cells." (PMID 29416741, 2018). "DANCR maintains the stemness features of hepatocellular carcinoma cells and promotes the invasion of prostate cancer cells." (PMID 29416741, 2018). "Our previous data demonstrated that lncRNA DANCR, which was first identified in hepatocellular carcinoma (HCC), promoted the cell proliferation and chondrogenic differentiation through up-regulating the expression of Smad3 and STAT3." (PMID 28674107, 2017). "The results showed that the expression level of DNACR was significantly correlated with higher pathological stage (p < 0.001), and indicated that DANCR may play a vital role in hepatocellular carcinoma progression." (PMID 38802416, 2024). "Moreover, expression of DANCR was dysregulated in several cancers, such as prostate cancer 13,14, hepatoma 15, glioma 16 and lung cancer." (PMID 37215458, 2023). "Notably, DANCR can also affect response of hepatocellular carcinoma cells to sorafenib through enhancing activity of IL-6/STAT3 signals." (PMID 35590326, 2022). "Moreover, two studies in papillary thyroid cancer and hepatocellular carcinoma reported down-regulation of this lncRNA, in spite of the bulk of evidence regarding up-regulation of DANCR in these two types of cancers." (PMID 35590326, 2022). "MiR-216a also interacted with lncRNA DANCR to promote hepatocellular carcinoma malignancy." (PMID 35381577, 2022). "Silencing DANCR expression could promote hepatocellular carcinoma cell apoptosis, meanwhile cell cycle progression was blocked in G1 phase." (PMID 33123287, 2020).
hepatocellular carcinoma (continued). "And DANCR was up-regulated in tumor tissues and plasma of patients with hepatocellular carcinoma, and plasma DANCR might be a useful biomarker for hepatocellular carcinoma diagnosis." (PMID 33123287, 2020). "In hepatocellular carcinoma, it is observed that down-regulated DANCR expression can boost cell apoptosis and cell cycle block in G1 which underlies that DANCR can promote tumor cell proliferation by inhibiting cell apoptosis and facilitating growth inhibition evasion." (PMID 31799189, 2019). "In human hepatocellular carcinoma cells, DANCR could bind to β-catenin mRNA and enhance its expression." (PMID 29416741, 2018). "DANCR functions as a regulator of cell stemness in human hepatocellular carcinoma." (PMID 29416741, 2018). "DANCR acts a regulator of β-catenin in hepatocellular carcinoma cells." (PMID 29416741, 2018). "Interestingly, even though lncRNA DANCR originally was identified as an oncogene in hepatocellular carcinoma, Sha S. and colleagues revealed that DANCR results in being upregulated also in TNBC, where it could represent a promising target for TNBC treatment." (PMID 37627209, 2023). "Therefore, we propose that the DANCR/miR‐27a‐3p/LIMK1 axis may have great influence in hepatocellular carcinoma progress." (PMID 31038266, 2019). "In addition, while DANCR and miR-216a interaction was previously reported in HEK293, breast, and hepatocellular carcinoma cells, we are the first to confirm this interaction in NSCLC." (PMID 33302540, 2020). "For example, DANCR can interact with the binding site of miR-199a/320a/214 in 3’UTR of CTNNB1 to inhibit the suppression of CTNNB1 by miRNAs, thus promoting stemness features of hepatocellular carcinoma." (PMID 30419948, 2018).
prostate carcinoma (21 papers, 2016 to 2024). A carcinoma that arises from epithelial cells of the prostate gland. "We observed that DANCR was significantly upregulated in PCa patient tissues and cell lines, indicating that DANCR is positively associated with progression of prostate cancer." (PMID 35571619, 2022). "Moreover, several lncRNAs, such as PCA3 and MALAT-1, can be used as diagnostic urinary biomarkers for prostate cancer, thus DANCR expression in the urine of prostate cancer patients should be measured and analyzed in the future." (PMID 27191265, 2016). "Conversely, in prostate cancer (PC) cells, DANCR overexpression impedes apoptosis and promotes malignant proliferation through competitive miR-214-5p inhibition." (PMID 38877534, 2024). "DANCR expression not only can be used for prostate cancer diagnosis, but also can predict poor prognosis of this type of cancer with high diagnostic value." (PMID 37025585, 2023). "Here, we report that the expressions of DANCR were significantly upregulated and miR-33b-5p were downregulated in prostate tumor specimens and cells as well as the Taxol-resistant prostate cancer cell line (PC3-TXR)." (PMID 35571619, 2022). "Bioinformatics analysis showed that the expression of DANCR was significantly elevated in diverse cancers particularly in prostate cancer from TCGA cancer database." (PMID 35571619, 2022). "Summarily, these results indicated that DANCR contributes to proliferation, migration, and Taxol resistance of prostate cancer cells." (PMID 35571619, 2022). "In this study, we aimed to investigate the roles of DANCR in glucose metabolism and Taxol resistance of prostate cancer." (PMID 35571619, 2022). "In summary, this study uncovered biological roles and molecular mechanisms of the DANCR-promoted chemoresistance, contributing to the development of noncoding RNA-based therapeutic strategies against drug-resistant prostate cancer." (PMID 35571619, 2022). "DANCR is also taken as an oncogenic lncRNA for several cancers, such as prostate cancer, gastric cancer and colorectal cancer." (PMID 31827393, 2019). "Previous reports showed that lncRNA DANCR was high-expressed in esophageal cancer, liver cancer, colorectal cancer, prostate cancer, retinoblastoma and so on, which indicated its potential correlation with the poor prognosis of patients." (PMID 31827393, 2019). "In human prostate cancer cells, DANCR binds to EZH2 and inhibits the expression of TIMP-2 by epigenetic silencing." (PMID 29416741, 2018). "Our results indicate that androgen-AR signaling up-regulates TIMP2/3 and DANCR impedes this up-regulation in prostate cancer cells." (PMID 27191265, 2016). "To determine the expression of DANCR in prostate cancer, we first searched multiple microarray data in the GEO database." (PMID 27191265, 2016). "All these data suggested that DANCR was down regulated by androgen-AR signaling pathway in prostate cancer." (PMID 27191265, 2016). "In the present study, we found that lncRNA DANCR expression increased in prostate cancer, moreover, DANCR promoted invasion and migration of prostate cancer cells in vitro and enhanced metastasis of xenograft prostate tumor in mouse model." (PMID 27191265, 2016). "Considering the critical role of TIMP2/3 (TIMP metallopepitidase inhibitor 2/3) plays in prostate cancer invasion, we focused on how DANCR represses the expression of these two genes." (PMID 27191265, 2016). "DANCR exerts its oncogenic effects via miR-185-5p/LASP1 axis in prostate cancer." (PMID 37025585, 2023). "Although studies have described that higher DANCR expression was positively correlated with diverse cancers, the roles of the aberrant upregulation of DANCR in Taxol-resistant prostate cancers remain largely unknown." (PMID 35571619, 2022). "Similarly, high expressions of DANCR were also detected in four prostate cancer cell lines compared with those from two normal prostate cell lines." (PMID 35571619, 2022).
prostate carcinoma (continued). "Our results consistently demonstrated that DANCR contributed to Taxol resistance of PCa, indicating that targeting DANCR might be applied as an anti-chemoresistance approach against prostate cancer." (PMID 35571619, 2022). "Recent studies demonstrated that DANCR facilitated malignancy of prostate cancer by targeting miR-185-5p, suggesting that blocking the DANCR-mediated molecular signaling pathways may contribute to chemotherapy of PCa." (PMID 35571619, 2022). "In addition, DANCR was upregulated in human prostate cancer tissues and cell lines and promoted invasion of prostate cancer by repressing expression of TIMP2/3." (PMID 32099526, 2020). "Besides, the discovery of DANCR/miR-34a-5p/JAG1 axis provides a novel perspective on the treatment of prostate cancer." (PMID 33292218, 2020). "In addition, DANCR has been reported to regulate paclitaxel sensitivity in prostate cancer via sponging miR-135a." (PMID 32766131, 2020). "Moreover, DANCR promoted prostate cancer cell invasion and migration in vitro and metastasis of tumor xenografts in nude mice." (PMID 33123287, 2020). "Remarkably, it is reported that DANCR could bind to enhancer of zest homolog 2 (EZH2) to regulate downstream genes at the epigenetic level in prostate cancer and gastric cancer." (PMID 31383847, 2019). "In this study, we detected the expression of DANCR in prostate cancer tissues and cell lines, and whether DANCR regulated the migration and invasion of prostate cancer in vitro and in vivo." (PMID 27191265, 2016). "Given that DANCR promotes the invasion while AR inhibits the invasion of prostate cancer cells, we hypothesized that DANCR may antagonize the effect of androgen-AR on invasion and migration of prostate cancer cells." (PMID 27191265, 2016). "However, it has been reported that enzalutamide promotes prostate cancer metastasis in different models, moreover, in our study we found that AR knockdown promotes invasion and migration of prostate cancer cells while DANCR knockdown reduces the promotion." (PMID 27191265, 2016). "LncRNA DANCR suppresses differentiation of epithelial cells, however, its function in prostate cancer development is still unknown." (PMID 27191265, 2016). "Because EZH2 is an important target in prostate cancer, our results suggest that knockdown of DANCR could strengthen the effect of EZH2 inhibitor on the suppression of prostate cancer metastasis." (PMID 27191265, 2016). "In the present study, we found the expression of DANCR increases in prostate cancer tissues and cells compared to normal prostate tissues and cells, moreover, DANCR promotes invasion and migration of prostate cancer cells in vitro and metastasis of tumor xenografts in nude mice." (PMID 27191265, 2016). "From the Oncomine database, we found that lncRNA DANCR is up-regulated in prostate cancer." (PMID 27191265, 2016). "Collectively, our results suggest that AR up-regulates TIMP2/3, suppresses invasion and migration of prostate cancer cells and inhibits the expression of DANCR; moreover, DANCR impedes the upregulation of TIMP2/3 and the suppression of invasion and migration by androgen-AR signaling pathway." (PMID 27191265, 2016). "Our results suggest that DANCR could be a potential target for preventing prostate cancer metastasis, and knockdown DANCR may lessen the potential side effect of AR inhibitor." (PMID 27191265, 2016). "In summary, our results indicate that DANCR promotes invasion and metastasis of prostate cancer, and DANCR could be a potential target for the treatment of prostate cancer." (PMID 27191265, 2016). "In addition, DANCR is reported to promote the invasion of prostate cancer cells." (PMID 29416741, 2018). "Finally we found that DANCR could be a potential target for preventing the metastasis of prostate cancer." (PMID 27191265, 2016). "Firstly we detected whether DANCR regulates invasion and migration of prostate cancer cells." (PMID 27191265, 2016).